ADAR (adenosine deaminase RNA specific)
Diseases named in the same sentence as ADAR in open-access papers (continued):
Sharing a sentence is not in itself a finding about the gene and the disease.
tumor (continued). "As such, it is tempting to speculate that these SpCas9 ADAR-targeting gRNAs could be effective in enhancing anti-tumor immune responses in the context of different therapeutic delivery modalities (e.g., lipid nanoparticles, viral vectors, RNP)." (PMID 39992915, 2025). "Furthermore, based on the biological function of ADAR to prevent constitutive recognition of self RNA, there is strong rationale that the effect of ADAR knockout in the tumor microenvironment would be observed in all cell types." (PMID 39992915, 2025). "However, the potential oncogenic effects of ADAR and its value in tumor therapy deserve further investigation and exploration." (PMID 37414093, 2023). "Notably, we identified the relationship between ADAR and the tumor microenvironment (TME), ICIs, and their regulatory role in immune infiltration and immunotherapy." (PMID 37414093, 2023). "In addition to causing coding alterations that support tumors, ADAR works to protect them by suppressing ISG-triggered immune responses and promoting tumor cell survival." (PMID 36999050, 2023). "ADAR can be a potential target in the development of anti-tumor therapy." (PMID 38203521, 2023). "Another consideration relies on the presence of an inflammatory microenvironment from the earliest stages of tumour progression, which makes it reasonable to assume that both APOBEC- and ADAR-derived signalling may be simultaneously active in tumour cells." (PMID 35955853, 2022). "Indeed, suppression of ADAR activity sensitizes tumor cells and virally infected cells to the immune response." (PMID 33921764, 2021). "Analysis of ADAR copy number in GC cell line were consistent with tumor specimens." (PMID 32410589, 2020). "Therefore, ADAR overexpression is not only a biomarker of tumor progression but also contributes to tumor progression." (PMID 32410589, 2020). "In tumor samples ADAR was expressed 2.8-fold higher than normal tissues." (PMID 32410589, 2020). "Broadly, these results suggest that the creation of miRNA targets may be an underappreciated function of ADAR and may help further elucidate the role of RNA editing in tumor pathogenicity." (PMID 30197877, 2018). "SRP9 sequencing chromatogram traces showed an adenine (in tumor DNA) and a guanine (in tumor RNA) substitution which might be attributed to ADAR, in fact ADAR carries out adenosine to inosine editions and inosine is read as guanosine by sequencing instruments." (PMID 23137041, 2012). "ADAR may edit the transcripts of oncogenes and tumor suppressor genes in tumor cells." (PMID 40618019, 2025). "This oncogenic–tumor-suppressive dichotomy underscores the importance of context in ADAR biology and highlights the potential of ADAR-targeted interventions whether through inhibition of ADAR1 or restoration of ADAR2—as promising strategies in precision oncology for GC." (PMID 40852728, 2025). "In addition, we illustrated the complex relationship between ADAR and the tumor immune microenvironment and propose the hypothesis that ADAR may be involved in the regulation of the tumor immunotherapy response." (PMID 37414093, 2023). "ADAR-related tumor therapy could also rely on the ZBP1 pathway inhibited by ADAR." (PMID 38203521, 2023). "Thus like Trex1, ADAR inactivates the stimuli at the origin of the IFN I production by tumor cells." (PMID 34249754, 2021). "For example, one study assessed the role of ADAR-mediated RNA editing in GC, identifying ADAR1 as an oncogene and ADAR2 as a tumor suppressor." (PMID 40852728, 2025). "Gene expression analysis revealed that ADAR and ADARB1 were significantly upregulated in tumor tissues compared to normal counterparts." (PMID 41300768, 2025). "In summary, GC presents a complex dual landscape for ADAR enzymes, wherein ADAR1 acts predominantly as a tumor promoter by silencing innate immune responses, stabilizing oncogenic transcripts, and enabling immune evasion." (PMID 40852728, 2025).
tumor (continued). "An extended analysis of additional type I IFN inducers showed that NLRC4 expression had the highest correlation overall across the various DC subsets and tumor types, followed by IFIH1, RIGI, TMEM173, and finally ADAR." (PMID 38652550, 2024). "We extract signatures of RNA single-base substitutions and link their aetiology to the activity of the RNA-editing enzymes ADAR and APOBEC3A, thereby revealing otherwise undetected ongoing APOBEC activity in tumours." (PMID 37046093, 2023). "A classic example of transcription factors regulating ADAR, AR served as a transcriptional activator of the ADAR1 promoter to promote HCC tumor growth both in vitro and in vivo." (PMID 36660243, 2023). "The relationship between ADAR mRNA expression and the abundance of infiltrating immune cells in CRC patients was explored by the Tumor Immune Estimation Resource, CIBERSORT, and single-gene gene set enrichment analysis (GSEA)." (PMID 36660243, 2023). "Cluster 3 had significantly lower expression level of ADAR and DDR but more TIICs presented in the tumor microenvironment." (PMID 37735483, 2023). "We observed significant over-expression of ADAR, ADARB1, DDX5/17/20, DGCR8, DICER1, DROSHA, EIF2C1-4 (AGO1-4), GEMIN4, POLR2A, TARBP2, TNRC6A and XPO5 in tumor tissue compared to adjacent mucosa." (PMID 31510013, 2019). "We propose that M1 and M2 TAMs secrete deaminase proteins (APOBEC, ADAR, AID) that are loaded into extracellular vesicles (EVs) within the pro‐ (M1) and anti‐ (M2) inflammatory tumour microenvironment." (PMID 30802996, 2019). "Consistent with our observations, a more recent report regarding ADAR-mediated RNA editing in GC progression revealed that ADAR1 plays an oncogenic and ADAR2 plays a tumor suppressive role in GC." (PMID 27863387, 2016). "We performed RNA editing analysis of the Gabra-3 I/M site (edited by both ADAR1 and ADAR2), the BLCAP Y/C, Q/R sites (edited by both ADAR enzymes) and the K/R site (edited mainly by ADAR2) in the tumor tissues of Case 4 and controls." (PMID 23697632, 2013). "In HNSCCs, the fold change was 1.23, indicating elevated ADAR expression in tumor tissues compared to non-cancerous controls." (PMID 41300768, 2025). "In CRC, ADAR-mediated RNA editing at 3ʹ-UTR of PVR could upregulate its expression by increasing the RNA stability, leading to tumor- and immune-related gene functions and pathways in CRC." (PMID 39126156, 2025). "The median expression of ADAR was 90.376 in tumor tissues versus 40.05 in non-cancerous tissues (p < 0.0001)." (PMID 41300768, 2025). "For example, in more aggressive undifferentiated TC, GSK-3β activity is higher, which may further promote the phosphorylation of ADAR and TRIM47-mediated degradation, thereby exacerbating tumor progression." (PMID 40618019, 2025). "More importantly, as ADAR enzyme targeting tends to destabilise IR-Alu originating dsRNA, there could be dependency on ADAR1 for tumour cells undergoing epigenetic therapy." (PMID 36307128, 2024). "In both TCGA-CESC and FUSCC cohorts, the expression pattern of dsRBPs-related subtypes or genes is consistent: ADAR and DDR subtypes are significantly downregulated in tumor tissues; whereas helicase, OAS RNAseL, PKR and RLR subtypes are significantly overexpressed." (PMID 37735483, 2023). "Interestingly, both ADAR and DDR showed relatively downregulated expression in tumor tissues compared to normal cervical tissues in both TCGA and FUSCC cohorts, consistent with previous study results." (PMID 37735483, 2023). "ADAR overexpression and amplification correlate with the main negative clinicopathological factors such as metastasis, tumor size and stage in GC patients." (PMID 32410589, 2020).
tumor (continued). "Finally, positive eQTLs were also observed between ADAR genotype and ADAR expression in EOC tumor tissue." (PMID 27911851, 2016). "Intriguingly, in the case of COG3, a thymine (in tumor DNA) was replaced by a cytidine (in tumor RNA) which cannot be carried out by ADAR nor APOBEC enzymes because APOBEC converts cytosine to uracile in RNA sequences." (PMID 23137041, 2012). "Thus, understanding how ADAR editing patterns are regulated, and how these alter TSM profiles will be important for advancing our knowledge of the role of ADARs during oncogenesis, even before tumor development." (PMID 27485054, 2016). "ADAR silent treatment could bypass the typical resistance of small-molecule anticancer drugs against the immune checkpoint blockade (ICB), such as the PD-1 checkpoint blockade, in tumor molecules together with PKR and MDA5 activation, thus resulting in tumor cell growth inhibition and inflammation." (PMID 38203521, 2023). "In clinical samples collected from 10 patients with HNSCC, the expression of all analyzed genes (ADAR, ADARB1, and ADARB2) varied between tumor and adjacent non-cancerous tissues." (PMID 41300768, 2025). "Based on TCGA clustering data for ADAR, ADARB1, and ADARB2, fold changes in gene expression between tumor and matched non-cancerous tissues were calculated using median expression values." (PMID 41300768, 2025). "Importantly, our validation using paired tumor and adjacent non-cancerous tissues confirmed this downregulation for ADARB2 but not for ADAR or ADARB1, suggesting that ADARB2 may represent the most robust biomarker candidate in this context." (PMID 41300768, 2025).
infection (69 papers, 2010 to 2026). The state of being infected such as from the introduction of a foreign agent such as serum, vaccine, antigenic substance or organism. "Analysis of ADAR-driven polymorphisms showed that ADAR editing plays an antiviral role in DMelSV infections, with intensity of editing appearing to differ across flies." (PMID 34694399, 2021). "In addition, we provide the first evidence that ADAR mutant animals have altered susceptibility to infection with several opportunistic human pathogens, suggesting a broader role of ADARs in altering physical barriers to infection to influence innate immunity." (PMID 38360623, 2024). "Subsequently, post-infection, though ADAR expression returns to pre-infection levels, ADAR editing remains dysregulated in some individuals." (PMID 42312023, 2026). "Our results demonstrate a consistent trend of elevated ADAR expression and reduced overall ADAR editing within each individual mid-infection." (PMID 42312023, 2026). "Upregulated genes in both infection and inflammation pathways were F2R, which links coagulation with inflammation; ADAR, crucial in antiviral immune responses; and FCAR, involved in IgA responses at mucosal sites." (PMID 41416938, 2025). "Meanwhile, upon infection, ADAR expression decreased in the conjunctiva, whereas ADARB1 expression decreased in the limbus and sclera." (PMID 38693480, 2024). "To date, many viruses were reported to interact with the host's ADAR enzymes during the infection and induce RNA editing of the virus' genome." (PMID 37859800, 2023). "The number of hyper-edited reads mirrored the increase of ADAR-compatible SNPs along both infections." (PMID 34696401, 2021). "ADAR editing was also described in infection by another member of the Nidovirales order, an arterivirus porcine reproductive and respiratory syndrome virus (PRRSV)." (PMID 34694399, 2021). "For both viruses, we showed that the impact of ADAR hyper-editing on transcripts increased along infection, while the level of transcript strandedness decreased for the same genes." (PMID 34696401, 2021). "For example, differences in viral delivery method and viral load could lead to differences in immune responses or patterns of infection that, in turn, influence ADAR editing." (PMID 37968596, 2023). "By tracing ADAR hyper-editing along OsHV-1 infection in C. gigas, we demonstrated that in the early stage of infection host RNAs are more impacted than viral RNAs, with viral-directed editing increasing along the time course and suggesting that at later stages ADAR1 will mostly target viral dsRNAs." (PMID 35379005, 2022). "Hyper-edited reads and ADAR-compatible SNPs increased along the infection for both viruses." (PMID 34696401, 2021). "In addition to investigating the mechanisms of regulation and the activity of ADAR during lytic infection, it would be of great interest to ascertain the biological impact of the A638T substitution in RTA." (PMID 24453964, 2014). "Furthermore, we examined whether infection-triggered dysregulation in ADAR editing persists or returns to pre-infection states post-viral clearance using publicly available whole blood RNA sequencing samples from forty-five, age-matched individuals." (PMID 42312023, 2026). "For example (presumably deleterious) sequence changes introduced early in the infection by ADAR editing as part of the antiviral defense may be proviral given the selective context imposed by a different arm of the immune response, for example, in immunocompromised individuals." (PMID 34694399, 2021). "Also ADAR p150 deaminase is induced upon infection/inflammation, further increasing inosine levels." (PMID 31703097, 2019). "Our results show that HSV-1 replication was ~10x and ~ 200x more productive in ADAR WT than in ADAR1 KO cells at high and low MOI infection, respectively." (PMID 40198737, 2025). "However, studies on the susceptibility of ADAR mutant animals to infection are largely lacking." (PMID 38360623, 2024).
infection (continued). "ADAR expression patterns in both EDB-2 and EDB-α-1 show an upregulation of this ISG following infection." (PMID 37876814, 2023). "In human ESCs, ADAR (also known as ADAR1) is one of the highly expressed ISGs in the absence of infection." (PMID 38399949, 2024). "In addition, PARP12, TAP1, CMPK2 and ADAR, which are crucial to restrict RNA virus replication, e.g. DENV、HIV、ZIKV, also upregulated in the early stages of HuB20 infection, indicating multiple antiviral responses was involved in this stage." (PMID 36544767, 2022). "MeV infections are best suited to characterize ADAR1 activity because under certain circumstances, the MeV negative-strand RNA genome can tolerate clusters of ADAR-diagnostic transitions." (PMID 30496178, 2018). "Of the interferon regulatory factor (IRF) genes annotated in KEGG, expression of IRF7 was significantly upregulated, and interestingly, all downstream transcriptional targets of IRF9 annotated in KEGG (MX1, OAS genes, ADAR, and PML) were consistently upregulated during acute infection." (PMID 30150281, 2018). "Infection could then lead to IFN-I production that could in turn activate bothPKR and ADAR-1 p150 in surrounding cells." (PMID 25389016, 2014). "Double-stranded RNA (dsRNA) is formed during infection with positive-strand RNA viruses such as severe acute respiratory syndrome coronavirus 2 (SARS-CoV-2) and may be subject to editing by a group of enzymes denoted adenosine deaminase acting on RNA (ADAR)." (PMID 35064076, 2022). "In another study DENV replication was found to be influenced by miR-3614-5p that downregulates both ADAR p110 and p150 expression, suggesting that the role of ADAR1 in DENV infectivity may change between early and later stages of infection from proviral to antiviral." (PMID 34694399, 2021). "First, productive infection (HCMV, OsHV-1, and HaHV-1), including the reactivation process (KSHV), triggers the expression of ADAR proteins, but not for all herpesviruses (HSV-1 and HSV-2)." (PMID 37896783, 2023). "In addition, how expression of the ADAR proteins is regulated during infection remains to be better understood (e.g., KSHV and HCMV induce ADAR1 expression during productive infection but with different protein forms, whereas HSV-1 does not affect ADAR1 levels)." (PMID 37896783, 2023).
neurological disorders (12 papers, 2016 to 2026). "The loss or dysfunction of ADAR enzymes in higher eukaryotes affects the editing efficiency of target genes, leading to some neurological diseases." (PMID 32806497, 2020). "The deletion or dysfunction of ADAR enzymes in higher eukaryotes can affect the efficiency of substrate editing and cause neurological disorders." (PMID 32806497, 2020). "Overall, harnessing endogenous ADAR with permanent AAV-driven CLUSTER guide RNAs in the CNS is an important next step toward the development of novel drug modalities that fight neurological diseases." (PMID 38997581, 2025). "However, current reports on the interaction of ADAR with substrate RNA, structural and functional identification, and subcellular localization have focused on the research into human nervous system diseases, and there are only a few reports for Drosophila." (PMID 32806497, 2020). "Elucidating the interaction mechanism between FAM20C and ADAR, SAFB and DAGLA holds crucial implications for understanding both the physiological roles of FAM20C in the nervous system and its pathological contributions to neurological disorders." (PMID 40511628, 2026).
immune diseases (7 papers, 2022 to 2026). "Previous studies also found that mutations in ADAR (Adenosine deaminase acting on RNA) can cause human immune diseases." (PMID 35711945, 2022).
metabolic disease (6 papers, 2018 to 2026). A congenital disorder (due to inherited enzyme abnormality) or acquired (due to failure of a metabolically important organ) disorder resulting from an abnormal metabolic process. "Hence, changes in ADAR activity in metabolic tissues during aging will result in risk of metabolic diseases." (PMID 32962255, 2020). "ADAR has been widely used in RNA editing therapy for diseases like cancer and metabolic disorders, as it exerts regulatory influence devoid of genome disruption." (PMID 37915585, 2023).
genetic disorder (5 papers, 2020 to 2025). "Programmable RNA editing leveraging ADAR enzymes represents a groundbreaking approach to treat genetic disorders at the RNA level, bypassing the potential risks associated with permanent DNA modifications." (PMID 39858624, 2025). "Programmable RNA editing, leveraging ADAR enzymes, presents a groundbreaking approach to treat genetic disorders at the RNA level, bypassing the potential risks associated with permanent DNA modifications." (PMID 39858624, 2025). "Herbert A. Mendelian Disease caused by variants affecting recognition of Z-DNA and Z-RNA by the Zα domain of the double-stranded RNA Editing Enzyme ADAR." (PMID 33983939, 2021). "Because of the association ADAR variants with interferon responses and Mendelian diseases, we tested, how many of the genes with DeepZ predicted Z-DNA in genes or promoters are Interferon response genes (IRGs)." (PMID 33154517, 2020). "The variants of ADAR with either absent or mutated Zα domain affect interferon responses and are associated with rare Mendelian diseases: Dyschromatosis Symmetrica Hereditaria, Aicardi-Goutières syndrome, and Bilateral Striatal Necrosis/Dystonia23." (PMID 33154517, 2020).
neurodegenerative disease (4 papers, 2018 to 2025). A disorder of the central nervous system characterized by gradual and progressive loss of neural tissue and neurologic function. "Observed lower levels of ADAR gene expression and overall decreased editing levels in PD samples could testify that mRNA modification patterns act as a part of the pathogenesis of this neurodegenerative disease." (PMID 35052353, 2021). "Therefore, ADAR gene expression aberrations could be included in the pathogenesis of this neurodegenerative disease." (PMID 35052353, 2021).